ANXA7 (annexin A7)
Diseases named in the same sentence as ANXA7 in open-access papers (continued):
Sharing a sentence is not in itself a finding about the gene and the disease.
tumor (continued). "This might point to the conclusion that the ANXA7 response as a tumor suppressor might be acting through a different mechanism other than cell cycle arrest." (PMID 39684934, 2024). "However, the mechanism through which ANXA7 functions as a tumor suppressor gene remains to be fully elucidated." (PMID 37240163, 2023). "Overall, this study provides valuable insights into the molecular mechanisms involved in the calcium- and phospholipid-binding properties of ANXA7 as a tumor suppressor and highlights the importance of the calcium signaling function of ANXA7 in preventing tumorigenesis." (PMID 37240163, 2023). "Exemplifying the member role of the annexin family, ANXA7 could translate conventional annexin properties such as PS/Ca binding and exocytosis into tumor suppression mechanisms." (PMID 37240163, 2023). "This fact, plus the high prevalence of tumors in the Anxa7 (+/−) knockout mouse model and the disorders of calcium metabolism in Anxa7 (+/−) mouse tissues appear to implicate a specifically thapsigargin-like mechanism for how the ANXA7 gene activates human tumor cell apoptosis." (PMID 37240163, 2023). "The expression level of ANXA7/8/13 is related to the stage of the tumour." (PMID 39290334, 2022). "In addition, DCBLD2, CASP7, TSC22D1, ANXA7, PRKAR2A, ZMYND11, and PAK2 have been reported to be tightly linked to tumor malignancy in previous studies." (PMID 35513372, 2022). "ANXA7 (annexin A7) is a ubiquitinated tumor suppressor gene." (PMID 35800363, 2022). "Altogether, AnxA7 has potential as a therapeutic target, but may also serve as a biomarker for the diagnosis, treatment and prognosis of a number of tumours." (PMID 33810523, 2021). "We investigated the effects of circ-ANXA7 knockdown on tumor growth of LUAD in vivo." (PMID 33536022, 2021). "Several in vivo studies support tumour suppressor roles for AnxA7." (PMID 33810523, 2021). "For instance, the initially generated heterozygous Anxa7+/− strain revealed a cancer-prone phenotype, with more than 20% of these mice developing spontaneous neoplasms, with lymphosarcoma being most frequent, especially in females, indicating gender- and possibly sex hormone -related differences." (PMID 33810523, 2021). "Recent studies indicate that ANXA7 is abnormally expressed in a variety of tumours." (PMID 33397392, 2021). "Heat map visualized the expression patterns of circ-ANXA7 between tumor and non-tumor samples." (PMID 33536022, 2021). "More importantly, in vivo, silencing circ-ANXA7 distinctly inhibited tumor growth." (PMID 33536022, 2021). "Many studies have found ANXA7 expression was abnormal in a variety of tumor tissues." (PMID 32526706, 2020). "Notably, the up-regulation of PTBP1 in GBM alters the splicing of Annexin A7 (ANXA7), a membrane-bound tumor suppressor protein involved in endosomal organization and function." (PMID 31861467, 2019). "Our current research is a further validation of our previous hypothesis and related findings; whereby, demonstrating the functional role of ANXA7 as a tumor suppressive gene." (PMID 30321230, 2018). "First, we tried to segregate the tumor grades based on ANXA7 expression level." (PMID 30321230, 2018). "However, our current TMA study indicated that the higher expression of ANXA7 also included the upregulation of tumor proliferation markers such as Bcl-2 and CD-10." (PMID 30321230, 2018). "SEC enhanced ITGB4 phosphorylation by binding to ANXA7 and activating ANXA7 GTPase in tumor cells." (PMID 26918348, 2016). "ANXA7, a member of the annexin family of calcium-dependent phospholipid binding proteins, codes for Ca2+ dependent GTPase, which involves several different roles in autophagy, exocytosis, carcinogenesis, and tumor suppression." (PMID 24963320, 2014). "High levels of Annexin A7 in a tumor correlate strongly with poor survival of patients." (PMID 24392146, 2014).
tumor (continued). "We investigated the time course of primary tumor formation in mice and found that on the 14th, 21st, and 28th days after tumor cell inoculation, both the 47 kDa and 51 kDa isoforms of Annexin A7 protein were detected in the “primary tumor” with different expression levels." (PMID 24188284, 2013). "Likewise, Annexin A7 expression was greater in FANXA7-control primary tumor cells than in lymph node-metastasized tumors (p < 0.05)." (PMID 24188284, 2013). "In addition, the expression of the 47 kDa and 51 kDa isoforms of Annexin A7 protein changed during tumor progression." (PMID 24188284, 2013). "ANXA7 upregulation may thus chemo-sensitize the tumor if p21 modulators are added to the treatment regimen, as they will counteract the c-MYC overexpression and oncogenic drive towards stemness, which has the same effect as c-MYC inhibition in these conditions." (PMID 39684934, 2024). "Therefore, we hypothesized that the action of the transfected ANXA7 gene on tumor cells may be to elevate cytosolic Ca2+ and to potentiate subsequent proapoptotic actions of the released calcium." (PMID 37240163, 2023). "Since ANXA1 was recently found to be downregulated in multiple human cancers in vivo, the fact that the ANXA1 N-terminal associates with cancer biomarkers cytokeratins 8 and 18 could provide some insights into tumor suppression by other annexins, including ANXA7." (PMID 37240163, 2023). "However, whether the molecular mechanisms for tumor suppression are also involved in the calcium- and phospholipid-binding properties of ANXA7 remain to be elucidated." (PMID 37240163, 2023). "Furthermore, sh-circ-ANXA7 distinctly decreased the tumor volume of LUAD mice model." (PMID 33536022, 2021). "Many reports support AnxA7 to have GTPase activity and contribute to the regulation of Ca2+ homeostasis, exocytic pathways, and prostaglandin production, with consequences for pancreatic and cardiac functioning and inflammatory myopathies, but also cell survival and tumour growth." (PMID 33810523, 2021). "In addition, ANXA7 may function in carcinogenesis by a discrete signaling pathway involving some tumor-suppressor, DNA-repair, and apoptosis-related genes." (PMID 26918348, 2016). "A series of functional studies demonstrated that circ-ANXA7 accelerated proliferation and invasion of LUAD cells as well as tumor growth." (PMID 33536022, 2021). "Conversely, the expression levels of ANXA6, ANXA7, and ANXA11 were significantly reduced in tumor tissues." (PMID 34484309, 2021). "To further observe the effect of ANXA7 on the growth of HCC cells in vivo, we established a xenograft tumor model, the control cells, upANXA7 cells, shANXA7 cells, and negative control cells in each group subcutaneously." (PMID 34716295, 2021). "PTBP1 promotes the skipping of exon 6 in ANXA7 and expression of this isoform diminishes the endosomal internalization of EGFR, thus enhancing signaling during tumor progression." (PMID 31861467, 2019). "Cross talk of ANXA7 with PTEN and EGF receptor led to constitutive activation of PI3K-AKT signaling, a central pathway of tumor cell survival and proliferation." (PMID 28915599, 2017). "To date, a number of genes have been identified that modulate lymphatic tumor metastasis when they are highly expressed in certain tumor cells, such as Ezrin, AF1QN, MMP-11, or Annexin A7." (PMID 24188284, 2013). "The expression intensity of Annexin A7 protein between high and low lymph node-metastasized tumors was also different: there was lower Annexin A7 expression in primary FANXA7-down tumor cells than in FANXA7-control tumors (p < 0.05)." (PMID 24188284, 2013). "In this study, we focused on the regulation of IP3Rs by ANXA7 and did not investigate other potential mechanisms of calcium signaling regulation or the role of other annexin family members in tumor suppression." (PMID 37240163, 2023). "DN-ANXA7J, which can inhibit wt-ANXA7-mediated phosphatidylserine liposome aggregation, lacked tumor suppressor effects." (PMID 37240163, 2023).
tumor (continued). "Further studies verified that circ-ANXA7 could induce proliferation and invasion of LUAD cells and promote tumor growth." (PMID 33536022, 2021). "To examine whether ANXA7 levels correlate with NHT response, we analyzed the expression of ANXA7 in terms of tumor specific survival in relation to NHT." (PMID 30321230, 2018). "In addition, haplo-insufficiency of Annexin A7 expression appears to drive disease progression to cancer because the genomic instability could lead to a discrete signaling pathway to reduce expression of the other tumor suppressor genes, DNA-repair genes, or apoptosis-related genes." (PMID 24188284, 2013). "In summary, our study indicated that Annexin A7 expression was able to inhibit HCC lymph node metastasis, indicating that the Annexin A7 gene might play an important role in the process of tumor lymph node metastases." (PMID 24188284, 2013). "Additionally, we analyzed mRNA data from tumor samples for these two markers (BRAF and ANXA7)." (PMID 39684934, 2024). "Thus, the in vivo data implied that Annexin A7 may play an important role in HCC lymphatic metastasis and play a tumor suppressor function in HCC." (PMID 24188284, 2013). "We hypothesized that the 4 C-terminal endonexin-fold repeats in ANXA7 (GX(X)GT), which are contained within each of the 4 annexin repeats with 70 amino acids, are responsible for both calcium- and GTP-dependent membrane fusion and the tumor suppressor function." (PMID 37240163, 2023). "In this study, we tested the hypothesis that the 4 endonexin-fold motifs in ANXA7, which are contained within each of the 4 C-terminal 70-amino-acid-long annexin repeats, are responsible for both calcium- and GTP-dependent membrane fusion and the tumor suppressor function." (PMID 37240163, 2023). "Therefore, we hypothesized that the 4 endonexin-fold motifs in ANXA7, which are contained within each of the 4 C-terminal 70-amino-acid-long annexin repeats, are responsible for both calcium- and GTP-dependent membrane fusion and the tumor suppressor function." (PMID 37240163, 2023). "However, the tumor suppressor mechanisms of Annexin A7 in HCC have not yet been elucidated." (PMID 24188284, 2013).
cancer (26 papers, 2011 to 2025). A tumor composed of atypical neoplastic, often pleomorphic cells that invade other tissues. "The loss of ANXA7 expression has been found to play a prognostic role in human cancers, including tumors from hormone-responsive tissues such as prostate and breast tissues." (PMID 37240163, 2023). "Accumulated evidence indicates that dysregulation of ANXA7 is associated with the occurrence, invasion, metastasis, and progression of a variety of cancers, but ANXA7 plays different roles in different tumors." (PMID 34716295, 2021). "The cancer-specific expression of ANXA7, a GTPase, has been described as a diagnostic marker of cancer and a potential target for cancer treatment." (PMID 28915599, 2017). "Thus, drug therapy targeting p21 and ANXA7 upregulation will be a great tool in causing cell cycle arrest and increasing sensitivity of cancer cells to pharmacological agents." (PMID 39684934, 2024). "Thus, the aggregation and fusion properties of the ANXA7 PS membrane can be directly linked to the ANXA7-mediated cancer-specific cell elimination." (PMID 37240163, 2023). "By switching from the net “−” to the net “+” when mutated, ANXA7 cannot bind to the inner layer of the plasma membrane and thus fails to start fusion and initiate the formation of cell–cell fusion, which is critical for cancer." (PMID 37240163, 2023). "Annexin A7 could also be associated with its mediation of exocytosis and secretion in prostate cells and possibly in other cancers." (PMID 24188284, 2013). "ANXA7-associated apoptotic and pharmacological manipulation has the potential to meet the urgent need for drugs that will preferentially kill cancer cells and shield normal cells, thus presenting a new mode of action that is vital in the management of cancer therapy." (PMID 37240163, 2023). "The aggregation of ANXA7 in these Ca2+-elevated axonal hot spots resembled the Ca2+-induced ANXA7 aggregates previously seen in cancer cells." (PMID 41188647, 2025). "The cancer-specific expression of ANXA7-GTPase, coupled with its importance in regulating cell death, cell motility, and invasion, makes it a useful diagnostic marker of cancer and a potential target for cancer treatment." (PMID 39684934, 2024). "The data indicated that the expression of ANXA7 is lower in cancer samples, whereas the expression level of BRAF remains constant." (PMID 39684934, 2024). "The cytotoxicity assay revealed that in DU145 cells, at 24 h, the vector alone and DN-ANXA7J had similar effects, while the addition of wt-ANXA7 killed the cancer cells effectively." (PMID 37240163, 2023). "Our studies with both human cancer cells and the Anxa7 knockout mouse have indicated the existence of a possible common deficit in calcium regulation." (PMID 37240163, 2023). "As expected, wt-ANXA7 demonstrated distinct effects on the lipid-relevant gene expression network in cancer cells." (PMID 37240163, 2023). "Consistent with the shielding effect of wt-ANXA7 on benign cell death, the wt-ANXA7-dependent G2 arrest was substantially diminished in PrEC compared with cancer cells." (PMID 37240163, 2023). "We discovered this gene (ANXA7) during the early 1990s and have been working to understand its cellular functions and functional role in different cancers." (PMID 37240163, 2023). "Nevertheless, drug targeting the GTPase activity of AnxA7 via small molecules hold promise for treatment of certain cancers and cardiovascular diseases (Section 8.5 and Section 8.6)." (PMID 33810523, 2021). "If its participation in sarcolemma repair remains to be established, ANXA7 has been shown to mediate membrane repair in cancer cells by enabling assembly of the ESCRT-III complex." (PMID 34067866, 2021). "To date, involvement of ANXA7 in membrane repair has been reported only in cancer cells, where it enables the formation of the ESCRT-III complex via the recruitment of the ALG-2 and ALIX proteins to the damaged membrane." (PMID 34067866, 2021).
cancer (continued). "The cancer-specific expression of ANXA7, coupled with its importance in regulating cell death, cell motility, and invasion, makes it a useful diagnostic marker of cancer and a potential target for cancer treatment." (PMID 30321230, 2018). "Since it is the BRAF mutation and not the expression that leads to cancer, we decided to look more closely at ANXA7." (PMID 39684934, 2024). "Similar to in vivo regulatory effects of ANXA1 peptides, ANXA7 protein segments could have therapeutic potential in cancer or other pathologies that involve PS membrane dynamics with phospholipid-associated signaling and metabolism." (PMID 37240163, 2023). "Similarly, annexin A7 appears to have a suppressor or promotor role depending on the type of cancer." (PMID 37833989, 2023). "The transfection of the ANXA7 gene into cancer cells also has a very similar sequence of actions." (PMID 37240163, 2023). "Further studies may elucidate pleiotropic ANXA7 effects on cell death/proliferation that are likely to share autophagy-relevant mechanisms with the major PI3K/Akt/mTOR players detected in cancer." (PMID 37240163, 2023). "Most remarkably, wt-ANXA7 induced tissue-specific alterations in the autophagy-relevant insulin/PI3K/Akt/mTOR signaling cascade (including also FOXO and PTEN) that has a central role in carcinogenesis as one of the most mutated systems in human cancer." (PMID 37240163, 2023). "Studies indicated that ANXA7 inhibition could inhibit the growth, proliferation and migration and promote apoptosis of cancer cells." (PMID 32526706, 2020). "Moreover, numerous examples of cancer-relevant genes affected at the splicing level (e.g. ANXA7, GLI1, MAX, KLF6) have been reported in GBM." (PMID 27287018, 2016). "We propose that aberrant SGK1 could affect reciprocal SGK1-FOXO3A-Akt regulation and, hence, further studies of ANXA7 TSG effects may lead to the compelling therapeutic modulation of SGK1/FOXO3A-mediated cell survival in cancer cells." (PMID 24864229, 2014). "However, there is no clear understanding of how the loss of ANXA7 induces different stages of cancer progression." (PMID 37240163, 2023). "However, how ANXA7 promotes different cancers remains to be fully understood." (PMID 37240163, 2023). "Membrane-linked protein A7 (ANXA7) is not consistently expressed in different types of cancer." (PMID 32526706, 2020). "With an N-terminal proline-rich LCD domain, the ANXA7 undergoes LLPS, which is triggered by millimolar of Ca2+ elevation in cancer cells." (PMID 41188647, 2025). "Finally, ANXA7 may have a bimodal role in the prognosis of different cancers." (PMID 37240163, 2023). "We applied the TIMER2 approach to analyze the expression status of ANXA7 and SRI in a panel of human cancers using the TCGA database and found the relative overexpression of ANXA7 and SRI in most human cancers." (PMID 34716295, 2021). "We identified a small molecule, SEC, with selective pro-apoptosis effects on cancer cells with high expression of ITGB4, both in vitro and in vivo, by triggering the binding of ITGB4 and ANXA7, ITGB4 nuclear trafficking, and pro-apoptosis gene expression." (PMID 26918348, 2016). "The C-terminal region of ANXA7 harbors Ca2+-sensitive Annexin repeats, which, at millimolar Ca2+ concentration, have been shown to trigger LLPS and promote droplet aggregation near plasma membrane (PM) lesions in cancer cells." (PMID 41188647, 2025). "In studies with the DU145 cancer cell line, we found that the effect of wt-ANXA7, but not DN-ANXA7J, on the enhanced release of cytochrome c had a threefold increase in comparison to the vector-alone control." (PMID 37240163, 2023). "ANXA7 does not consistently function in different types of cancer." (PMID 33397392, 2021).
brain disease (1 paper, 2018). "However, only a few studies of ANXA7 in brain disease have been reported." (PMID 29896083, 2018).
neurodegenerative disease (1 paper, 2025). A disorder of the central nervous system characterized by gradual and progressive loss of neural tissue and neurologic function. "This suggests that boosting ANXA7 levels could represent a potentially effective therapeutic strategy for treating TIA1 aggregation-related neurodegenerative diseases." (PMID 41188647, 2025). "In this study, we reveal that ANXA7 enhances a dynein-driven RNP transport mechanism related with the degradation of these RNPs, thereby counteracting TIA1 aggregation in axons and providing a potential strategy to target and eliminate pathogenic aggregates underlying neurodegenerative diseases." (PMID 41188647, 2025).
ANXA7 also shares sentences with these, for which no sentence is quoted: nasopharyngeal carcinoma (4 papers); brain injury (2); cardiovascular diseases (2); inflammatory myopathies (2); agoraphobia (1); cerebrovascular disease (1); cervical squamous cell carcinoma (1); cervix carcinoma (1); Cognitive impairment (1); colitis (1); depression (1); Fanconi anemia (1); Intraventricular hemorrhage (1); ischemia (1); lung adenocarcinoma (1); myocardial infarction (1); non-small cell lung carcinoma (1); ovarian serous adenocarcinoma (1); retinal degeneration (1); spinal cord injury (1).